SNTB2 (syntrophin beta 2)
Description:
Adapter protein that binds to and probably organizes the subcellular localization of a variety of membrane proteins. May link various receptors to the actin cytoskeleton and the dystrophin glycoprotein complex. May play a role in the regulation of secretory granules via its interaction with PTPRN.
Synonyms: SNT3; SNTL; D16S2531E; SNT2B2; EST25263
Tractability: Antibody: its Gene Ontology location is reachable by antibodies, with high confidence; UniProt places it where antibodies can reach, with medium confidence. PROTAC: ubiquitination databases record sites on it; its protein half-life has been measured.
Gene: Protein-coding gene on chromosome 16 (69,187,142 to 69,309,052, forward strand). Ensembl gene ENSG00000168807.
Subcellular location: Membrane; Cytoplasmic vesicle, secretory vesicle membrane; Cell junction; Cytoplasm, cytoskeleton
Subcellular location (Human Protein Atlas): Basal body; Centriolar satellite; Golgi apparatus; Plasma membrane; Nucleoplasm; Primary cilium transition zone
Pathways (Reactome):
Extracellular matrix organization: Formation of the dystrophin-glycoprotein complex (DGC)
Gene Ontology:
Molecular function: protein binding; RNA binding; structural molecule activity
Cellular component: cytoplasm; focal adhesion; plasma membrane; protein-containing complex; dystrophin-associated glycoprotein complex; membrane; synapse; anchoring junction; cytoskeleton; transport vesicle membrane
Genetic constraint (gnomAD): Loss-of-function variants: 33 observed, 41.84 expected, observed/expected ratio (o/e) 0.79, 90% interval 0.6 to 1.05. The upper end of that interval is the gene's LOEUF score, 1.05, which puts it in group 4 of 6, group 1 being the genes least tolerant of losing a copy. Missense variants: 580 observed, 599.56 expected, observed/expected ratio (o/e) 0.97, 90% interval 0.9 to 1.04. Synonymous variants: 279 observed, 241.83 expected, observed/expected ratio (o/e) 1.15, 90% interval 1.04 to 1.27.
Homologues: Orthologues: chimpanzee SNTB2 (99% identical), macaque VPS4A (99% identical), dog SNTB2 (98% identical), pig SNTB2 (98% identical), guinea pig SNTB2 (96% identical), rat Sntb2 (95% identical), rabbit SNTB2 (81% identical), mouse Sntb2 (80% identical), zebrafish sntb2 (59% identical), tropical clawed frog sntb2 (54% identical), Drosophila melanogaster Syn1 (41% identical), Caenorhabditis elegans stn-1 (34% identical). Paralogues in human: SNTB1 (54% identical), SNTA1 (45% identical), SNTG2 (24% identical), SNTG1 (23% identical).
Diseases named in the same sentence as SNTB2 in open-access papers:
SNTB2 is named in the same sentence as 10 diseases in open-access papers, as found by Europe PMC text mining. Sharing a sentence is not in itself a finding about the gene and the disease. The quoted sentences say what the papers report.
Obesity (2 papers, 2018 to 2024). Accumulation of substantial excess body fat. "Syntrophin Beta 2 (SNTB2) suggestes a role in ERK and SR-BI level, and sphingomyelin metabolism in obesity and have been proved to affect the activity of ABCA1 by stabilizing ABCA1 protein, which affect the catabolism of LDL-C level." (PMID 30498476, 2018).
atherosclerosis (1 paper, 2018). A disease characterized by the build-up of fatty material and calcium deposition in the arterial wall resulting in partial or complete occlusion of the arterial lumen. "Previous finding reported SNTB2 involved in atherosclerosis, and that its risk factors in atherosclerosis include higher plasma urate level which has linked to lower risk of PD in men." (PMID 29653596, 2018).
lung carcinoma (1 paper, 2025). "For patient P03, the ImmuniT platform also uncovered two novel neoantigens, MED23 and SNTB2, both implicated in lung cancer progression." (PMID 41012124, 2025).
metastatic melanoma (1 paper, 2023). A melanoma that has spread from its primary site to another anatomic site. "As for the immunomodulatory mechanism of SNTB2, SLC1A4, LAMP3 and CCDC69 in metastatic melanoma or macrophages, it was not specifically elucidated, though it is still a promising research direction." (PMID 37762054, 2023).
retina degeneration (1 paper, 2014). "SNTB2 is necessary for eye development in Drosophila, SLC1A2 is a glutamate transporter and glutamate reduction was observed in Müller cell in rd1 retina, and CDK6 is involved in retina degeneration in mice." (PMID 24581223, 2014).
viral infection (1 paper, 2025). "Several studies have reported an interaction between the PDZ domain of MAST kinases and proteins such as USP1, SNTB2, PTEN, RABV-G, NHE3, and ACE2, which are involved in diverse processes like longevity, neurite outgrowth, and viral infection." (PMID 41237908, 2025).
cancer (2 papers, 2013 to 2023). A tumor composed of atypical neoplastic, often pleomorphic cells that invade other tissues. "Furthermore, SNTB2 plays a critical role in the radioresistance of cancer cells." (PMID 36999050, 2023).
SNTB2 also shares sentences with these, for which no sentence is quoted: Insulin resistance (1 paper); melanoma (1); neurodevelopmental disorder (1).